BDNF (brain derived neurotrophic factor)
Diseases named in the same sentence as BDNF in open-access papers (continued):
Sharing a sentence is not in itself a finding about the gene and the disease.
Obesity (continued). "The prominent role of BDNF in the regulation of food intake is further strengthened from observation by using icv infusion of BDNF that resulted in suppression of weight gain in rat and second from BDNF heterozygous mice displaying 50% loss of BDNF expression and age-dependent obesity." (PMID 32272767, 2020). "Interestingly, three of the obesity-associated CpGs were located within two of the numerous promoters of BDNF, and differential BDNF transcripts are expressed at different time points and in different cellular compartments." (PMID 32942585, 2020). "We uncovered whether the underlying obesity decreased the tissue content of BDNF and increased phosphorylated Tau in the frontal cortex by immunohistochemistry on brain slices." (PMID 32927823, 2020). "In human studies, BDNF deficiency or functional impairment contributes to the pathogenesis of obesity, metabolic diseases, insulin resistance, eating disorders, and substance additive disorders, but the changes in BDNF after weight loss through different weight reduction methods are variable." (PMID 32210348, 2020). "Mutations in the BDNF gene have been found to be associated with hyperphagia and obesity in people, while exogenous BDNF administration was shown to induce weight loss in animal models, although studies on serum BDNF levels in obese individuals have yielded ambiguous results." (PMID 32226399, 2020). "Mutations in BDNF gene have been associated with monogenetic obesity." (PMID 32982666, 2020). "As review by Xu and Xie, genetic mutations in human BDNF and its receptor TrkB result in morbid early-onset obesity; furthermore, genome wide associated studies (GWAS) have identified single nucleotide polymorphisms (SNPs) in or near BDNF to be associated with increased body mass index (BMI)." (PMID 33297933, 2020). "Interestingly, this effect is normalized in men with obesity following a weight loss intervention in proportion to the magnitude of weight lost, suggesting that hyperglycemia differentially affects circulating BDNF based on weight status." (PMID 33013465, 2020). "In humans, a polymorphism in the BDNF gene has been linked to obesity." (PMID 31572115, 2019). "Furthermore, BDNF-deficient mice exhibit obesity due to overfeeding, a phenotype that is mirrored in mice deficient for the high-affinity BDNF receptor TrkB." (PMID 31572115, 2019). "In addition, it is worth noting that a SNP (rs4074134) near the BDNF gene was recently reported to be associated with T2DM independently of obesity in the Chinese Han population." (PMID 29423073, 2018). "Indeed, BDNF is an anorexigenic factor, and low levels of BDNF in hippocampus and dorsal-vagal complex as well as mutation in the BDNF gene are associated with hyperphagia, weight gain and obesity." (PMID 30347685, 2018). "The current opinion that obesity is associated with lower levels of circulating BDNF, and that restoring its physiological levels by administration of exogenous BDNF may prevent the detrimental effect of the metabolic syndrome should be considered carefully." (PMID 30081509, 2018). "The primary aim of this study was to quantify the independent contribution that demographic, anthropometric, and metabolic indicators make toward the prediction of change in serum BDNF levels after a 6-month exercise intervention among a high-risk population of adolescents with obesity." (PMID 30363954, 2018). "Interestingly, the BDNF Val66Met polymorphism has been studied for possible association with obesity, a key pathogenic factor in development of T2DM, but reports are contradictory." (PMID 29423073, 2018). "Moreover, no indicators of glucose regulation were reported, thus precluding an evaluation of how changes in BDNF relate to changes in diabetes risk in the adolescents with obesity." (PMID 30363954, 2018). "Indeed, BDNF haploinsufficiency or missense mutations in its receptor, TrkB, are associated with hyperfagia, weight gain, and obesity both in human and in mouse models." (PMID 30081509, 2018).
Obesity (continued). "The associated genetic markers from BDNF may have different effects, and accumulated mutations may provide a whole contribution to the obesity induced by AAPD." (PMID 28327672, 2017). "Several previous studies had implicated that the derived Met allele of BDNF gene might down-regulate BDNF, raise blood glucose concentration and predispose individuals to obesity." (PMID 28056856, 2017). "Hence, the following study about the function of the genetic variants will be necessary to elucidate the mechanism how the genetic variants in BDNF medicate signaling pathway and lead to obesity." (PMID 28327672, 2017). "Despite being an obesity predisposing gene, BDNF may be related to increased PA levels in our cohort." (PMID 26727462, 2016). "Animal models have demonstrated that BDNF haploinsufficiency leads to a reduction in hypothalamic expression of BDNF mRNA that causes hyperphagia and obesity that could be reversed by intracerebroventricular infusions of BDNF." (PMID 27685845, 2016). "As decreased expression of TrkB by adipose tissue was associated with obesity, we hypothesized that BDNF might positively regulate energy metabolism by acting on adipocyte TrkB." (PMID 28721258, 2015). "Reduced serum BDNF levels were shown to be phenotypically associated with an impaired cognitive functioning and hyperactivity, but also with severe obesity, while increased serum BDNF levels were found in overweight to obese individuals after losing weight after a reduced-calorie diet." (PMID 26190989, 2015). "Genes functioning in the leptin-melanocortin pathway such as those encoding leptin (LEP), leptin receptor (LEPR), melanocortin 4 receptor (MC4R), pro-opiomelanocortin (POMC) and brain-derived neurotrophic factor (BDNF) have been implicated in the monogenic form of obesity." (PMID 26363598, 2015). "In addition, reduced expression of BDNF was described in association with obesity in the leptin receptor deficient mouse, the Alzheimer disease mouse and the Sf-1 KO mouse." (PMID 25122490, 2014). "In addition to expression of hippocampal BDNF, its receptor TrkB was decreased in leptin deficient mice exhibiting obesity, while levels of NT-3 were intact." (PMID 25309465, 2014). "Human BDNF haploinsufficiency was linked to elevated food intake and obesity." (PMID 25386150, 2014). "Moreover, severe hyperphagia and obesity develop in individuals with BDNF haploinsufficiency, or a missense mutation of the TrkB gene in human." (PMID 25153796, 2014). "We also observed an odds ratio of 1.92 per-additive alleles (95% CI: 1.32–2.81) for rs10767664 located in the BDNF gene, which despite the low sample size provided strong evidence of association with obesity (P = 0.0079, after adjusting for multiple comparisons)." (PMID 25484485, 2014). "Obesity in mice with BDNF deficiency is associated with hyperglycemia and impaired glucose tolerance, and this glucose phenotype is at least in part attributable to the direct action of BDNF on glucose homeostasis." (PMID 23519010, 2013). "Strong genetic data link the Tyrosine kinase receptor B (TrkB) and its major endogenous ligand brain-derived neurotrophic factor (BDNF) to the regulation of energy homeostasis, with loss-of-function mutations in either gene causing severe obesity in both mice and humans." (PMID 23700410, 2013). "It is critical to understand the changes in the structure and function of the neural circuitry for reward when BDNF signaling is impaired, which leads to hyperphagia on high-fat diet, since excessive intake of high fat diet is likely an important cause of the obesity pandemic in humans." (PMID 23519010, 2013). "These variations in BDNF structure might affect its protein activity and mRNA transcription pattern in a way that increases the risk for obesity and T2DM." (PMID 23431394, 2013). "We replicated a previously reported association between BDNF-rs4074134 and obesity." (PMID 23431394, 2013).
Obesity (continued). "A critical role for endogenous BDNF in the regulation of feeding behavior was demonstrated in mice with reduced BDNF levels, such as heterozygous BDNF (Bdnf+/−) mice, which had increased risk of obesity resulting from increased food intake, concomitant with elevated serum leptin and insulin levels." (PMID 23519010, 2013). "Deficiencies in BDNF signaling are also associated with obesity in humans." (PMID 23519010, 2013). "The obesity risk allele of BDNF rs4923461 protected against type 2 diabetes, which could suggest neuronal and peripheral distinctive ways of actions for the protein." (PMID 21912638, 2011). "As obesity is a strong risk factor of type 2 diabetes we also examined associations with risk of type 2 diabetes, and unexpectedly established a BMI-dependent borderline association with the BDNF rs4923461 obesity risk allele and reduced risk of type 2 diabetes." (PMID 21912638, 2011). "Our analyses also suggested that although rs4923461 in BDNF increase the risk of obesity, it conversely protect against type 2 diabetes, which could be through different neuronal and peripheral mechanisms." (PMID 21912638, 2011). "Given the strong neuroprotective role of brain-derived neurotrophic factor (BDNF) and exercise training as a known modulator for its elevation, this systematic review sought to examine the strength of the association between exercise and BDNF levels in healthy people with overweight and obesity." (PMID 38618555, 2024). "Among its genetic variants, the BDNF Val66Met polymorphism is widespread in the population and has been associated with the onset and aggravation of diverse pathologies, including metabolic conditions like obesity and diabetes, cardiovascular ailments, cancer, and an array of psychiatric disorders." (PMID 38988887, 2024). "Interestingly, heterozygous BDNF knockout mice gain more weight than control mice and several of the heterozygous BDNF-deficient mice become obese, but infusion with BDNF was observed to transiently reverse the eating behavior and obesity." (PMID 39194496, 2024). "Likewise, interventions that boost BDNF expression, such as physical exercise, have been associated with enhanced cognitive performance and mood in both healthy individuals and those grappling with obesity." (PMID 38785805, 2024). "Hence, genetic deposition or metabolic status like obesity that might result in low intramyocellular BDNF content should be considered potential risk factors for muscle inflammation when the subject faces repetitive exercise." (PMID 39531828, 2024). "Regarding the relationship between BDNF polymorphisms and obesity, the BDNF G196A (Val66Met) polymorphism (rs6265) was chosen as one of the two tags in the present study because this common BDNF polymorphism affects intracellular packaging of the precursor of BDNF (proBDNF)." (PMID 37007871, 2023). "Thus, we investigated whether the relationship between serum BDNF levels, hepatic enzymes, and fibrosis-related indices is an epiphenomenon associated with obesity and blood glucose levels." (PMID 35998179, 2022). "There is some evidence that the BDNF gene and its protein product may be implicated in obesity." (PMID 36676721, 2022). "Thus, there is rationale to hypothesize that African American/Black adults may exhibit lower levels of BDNF due to greater incidences of vascular-related risk factors and obesity, which taken together, may lead to cognitive dysfunction." (PMID 36092801, 2022). "Also, the gene BDNF has been associated with the development of obesity, while the deactivation of BDNF could promote cardiac remodeling after MI and improve post-MI survival." (PMID 33842562, 2021). "Thus, we hypothesized that SNPs on BDNF might be associated with weight gain/obesity related to smoking cessation." (PMID 34525971, 2021). "However, the association between circulating levels of BDNF and obesity is still unclear." (PMID 35127775, 2021).
Obesity (continued). "Likewise, the rs6265 variant (G > A) in the coding region of the BDNF gene that involves Valine to Methionine substitution at the 66th amino acid position (Val66Met) of the N-terminal domain of pro-BDNF has also been linked with obesity." (PMID 33859285, 2021). "In fact, it has been postulated that BDNF might perform functions related to satiety induction and increased energy expenditure in obesity, while S100B seems to be associated with inflammatory markers, and positively associated with body mass index (BMI), and with serum leptin levels." (PMID 34591410, 2021). "Furthermore, obesity is associated with decreased levels of BDNF." (PMID 32927823, 2020). "Also, BDNF could be important for the regulation of energy homeostasis, since diminished BDNF levels are associated with disorders of energy metabolism such as obesity and hyperglycemia." (PMID 31440144, 2019). "Notably, other loci such as MC4R, PCSK1, and BDNF, are well known to be associated with severe early-onset obesity and harbor genes involved in the regulation of leptin-melanocortin pathways in the hypothalamus, thus are thought to affect body weight largely through impacting appetite." (PMID 31285522, 2019). "This functional interrelation is also evidenced by reported roles of BDNF in decreasing food consumption, regulation of glucose levels, increase of cerebral energy expenditure, and by implications of a deficient BDNF-trkB signaling in the onset of metabolic disorders, such as obesity." (PMID 31052460, 2019). "Similarly, differences in allelic prevalence of BDNF polymorphisms that might affect protein circulating levels and are associated with obesity were found among ethnic groups." (PMID 30081509, 2018). "In conclusion, exercise-induced reductions in some diabetes risk factors were associated with increases in BDNF in adolescents with obesity, suggesting that exercise training may be an effective strategy to promote metabolic health and increases in BDNF, a protein favoring neuroplasticity." (PMID 30363954, 2018). "Accordingly, exercise may improve diabetes risk factors and obesity directly through its effects on glucose regulation and energy expenditure, as well as indirectly via its effects on BDNF and improvements in glucose regulation and metabolic health from exercise." (PMID 30363954, 2018). "Indeed, BDNF-haploinsufficient mice are obese and diabetic and exhibit hyperphagic behavior, and expression of the BDNF gene variant (Val66Met) is significantly associated with measures of obesity in human pediatric and adult cohorts." (PMID 30363954, 2018). "Thus, they suggest that due to increased inflammatory condition, peripheral blood mononuclear cells indicate BDNF and IL-6 expression, which may play a collaborative neuroprotective effect associated with obesity." (PMID 29062839, 2017). "For example, SNP rs2030323, located in the intron of BDNF (brain derived neurotrophic factor) which encodes a member of the nerve growth factor family of proteins, has C/A alleles in which the C allele was tested in European and East Asian populations to increases obesity risks." (PMID 29126384, 2017). "In contrast to the known role of the BDNF/TrkB axis in the central nervous system, deletion of TrkB from adipocytes led to decreased food intake and reduced accumulation of fat in female mice fed a high-calorie diet, thereby improving various metabolic abnormalities associated with obesity." (PMID 28721258, 2015). "Furthermore, brain-specific deletion of Bdnf, deletion of dendritic BDNF mRNA, shRNA-mediated knockdown of BDNF using a viral vector, and a hypomorphic allele of Trkb that expresses only a quarter of TrkB all result in hyperphagia, obesity, and metabolic imbalances such as hyperglycemia." (PMID 25309497, 2014).
Obesity (continued). "A recent study found that the association between BDNF rs6265 variant and obesity-related traits was modified by polyunsaturated fatty acid intakes among men in the Boston Puerto Rican population, which provides some further support for a role for BDNF in energy balance regulation and obesity." (PMID 23861046, 2013). "Interestingly, FTO, MC4R and BDNF loci were most significantly associated with class III obesity." (PMID 23950976, 2013). "Hence, tissue specific up-regulation of endogenous BDNF levels in peripheral tissues could explain this BMI-dependent protective effect on type 2 diabetes for the reported BDNF obesity risk allele (rs4923461)." (PMID 21912638, 2011). "Studies over the past decade using BDNF knockout mice have shown that they can develop obesity through a deficit in satiety." (PMID 39857710, 2025). "Progression from HFD-mediated obesity to STZ-induced diabetes in mice demonstrated epigenetic dysregulation of the neuroprotective protein BDNF." (PMID 41277875, 2025). "Nonetheless, the relationship between blood BDNF levels and obesity remains debated, and the effects of energy-restricted diet on BDNF are not fully understood." (PMID 40697550, 2025). "In female mice, the inhibition of BDNF in hypothalamic FezF1 neurons result in protection against diet-induced obesity due to a reduction in food intake and increased spontaneous ambulatory activity, whereas in males it leads to increased cold tolerance." (PMID 41219904, 2025). "This study aims to examine the relationship between blood BDNF levels and obesity and to assess the effect of energy-restricted diets on BDNF levels." (PMID 40697550, 2025). "The Fezf1-specific knockout of BDNF resulted in increased cold tolerance in males, and protection against diet-induced obesity due to a reduction in food intake and increased spontaneous ambulatory activity in females." (PMID 41219904, 2025). "While BDNF levels are reduced in obesity and type 2 diabetes, they are elevated in NAFLD and increase with disease severity." (PMID 41515940, 2025). "Experimental studies support this by showing that high-triglyceride diets can exacerbate obesity-related cognitive impairment, reduce BDNF levels, impair cellular proliferation, and promote hippocampal apoptosis." (PMID 41007867, 2025). "With regards to obesity, maternal smoking has been associated with hypermethylation of the insulin-like growth factor 2 (IGF2) promoter and brain-derived neurotrophic factor (BDNF) gene involved in growth and satiety regulation." (PMID 40806516, 2025). "We enrolled 233 individuals with normal weight (n = 102), overweight (n = 52), and obesity (n = 69) and measured their serum BDNF levels." (PMID 40697550, 2025). "This work offers valuable insights into the relationship between blood BDNF levels, obesity, and energy restriction in a real-world context." (PMID 40697550, 2025). "The correlation between blood BDNF levels and obesity is a topic of ongoing debate in the literature." (PMID 40697550, 2025). "Systemic BDNF injections in mouse models of obesity and diabetes decrease blood glucose levels by enhancing muscle glucose uptake." (PMID 40171198, 2025). "Ablation of SH2B1 resulted in energy imbalance, obesity, and metabolic dysfunction via repressing BDNF action in mice." (PMID 41410190, 2025). "SNPs including fat mass and obesity-associated (FTO), brain-derived neurotrophic factor (BDNF), and melanocortin 4 receptor (MC4R) have also been implicated in obesity in the Japanese population." (PMID 40074353, 2025). "Yet, others have found that BDNF levels rise with aerobic exercise along with improvements in mood in individuals with obesity." (PMID 41277875, 2025). "Moreover, obesity in children is associated with chronic low-grade inflammation, insulin resistance, and impaired neurotrophic factor signaling, which may attenuate the normal BDNF response usually induced by exercise." (PMID 40724649, 2025).